KLHL30 (kelch like family member 30)
Synonyms: FLJ43374
Tractability: Small molecule: it belongs to a druggable protein family.
Gene: Protein-coding gene on chromosome 2 (238,138,668 to 238,152,947, forward strand). Ensembl gene ENSG00000168427.
Subcellular location (Human Protein Atlas): Centriolar satellite
Gene Ontology:
Molecular function: ubiquitin-like ligase-substrate adaptor activity
Biological process: proteasome-mediated ubiquitin-dependent protein catabolic process
Cellular component: Cul3-RING ubiquitin ligase complex; cytoplasm
Genetic constraint (gnomAD): Loss-of-function variants: 57 observed, 43 expected, observed/expected ratio (o/e) 1.33, 90% interval 1.07 to 1.65. The upper end of that interval is the gene's LOEUF score, 1.65, which puts it in group 6 of 6, group 1 being the genes least tolerant of losing a copy. Missense variants: 722 observed, 651.93 expected, observed/expected ratio (o/e) 1.11, 90% interval 1.04 to 1.18. Synonymous variants: 315 observed, 300.65 expected, observed/expected ratio (o/e) 1.05, 90% interval 0.95 to 1.15.
Homologues: Orthologues: chimpanzee KLHL30 (99% identical), macaque KLHL30 (97% identical), pig KLHL30 (91% identical), dog KLHL30 (90% identical), guinea pig KLHL30 (88% identical), mouse Klhl30 (88% identical), rat Klhl30 (88% identical), rabbit KLHL30 (79% identical), tropical clawed frog klhl30 (59% identical), zebrafish klhl30 (55% identical). Paralogues in human: KLHL21 (38% identical), KLHL24 (29% identical), KLHL38 (29% identical), KLHL35 (28% identical), KLHL2 (28% identical), KLHL1 (27% identical), KLHL29 (27% identical), KLHL5 (27% identical), KLHL20 (27% identical), KLHL4 (27% identical), KLHL3 (26% identical), KLHL12 (26% identical), and 42 more.
Diseases named in the same sentence as KLHL30 in open-access papers:
KLHL30 is named in the same sentence as 6 diseases in open-access papers, as found by Europe PMC text mining. Sharing a sentence is not in itself a finding about the gene and the disease. The quoted sentences say what the papers report.
arthrogryposis (1 paper, 2022). A rare, non-progressive congenital disorder characterized by multiple joint contractures which are present at birth. "These four altered genes (TPM2, KLHL30, KLHL40, and CACNA1S), detected using WES, are expressed in the muscle and have been associated in the literature with akinesia, NM, and arthrogryposis." (PMID 36292632, 2022).
glioma (1 paper, 2020). A benign or malignant brain and spinal cord tumor that arises from glial cells (astrocytes, oligodendrocytes, ependymal cells). "Klhl21 is known to bind E3 ubiquitin ligase through Cul3 and Klhl30 has been identified as a circadian pathway gene involved in the onset of glioma." (PMID 33043001, 2020).
neuroblastoma (1 paper, 2025). Neuroblastoma (NB) is the most common solid, extracranial childhood tumor. "Subsequent Kaplan-Meier analysis revealed that high expression of KLHL37, rather than KLHL12 or KLHL30, was significantly associated with poor overall survival (OS) of patients with neuroblastoma." (PMID 40493396, 2025).
cancer (2 papers, 2018 to 2020). A tumor composed of atypical neoplastic, often pleomorphic cells that invade other tissues. "Therefore, KLHL30 was involved in the division of cancer cells, and its high expression was a disadvantage for prognosis, as shown in the proposed model." (PMID 32852285, 2020). "Eight of these had decreased expression in cancer (KLHL3, KLHL4, KLHL13, KLHL14, KLHL29, KLHL30, KLHL32, and KLHL33) while four genes (ENC1, KLHL12, KLHL17, and KLHL35) had patterns of up-regulated gene expression." (PMID 30647843, 2018). "Finally, four key genes (KLHL30, PLN, LYVE1, and TIMD4) and four clinical factors (Asian, age, grade, and bilirubin) were included in the prognostic model, namely Immunity and Cancer-stem-cell Related Prognosis (ICRP) score." (PMID 32852285, 2020).
tumor (2 papers, 2020 to 2025). "Moreover, we found that KLHL12 and KLHL37 had higher expression levels in tumor tissues compared with levels in adjacent tissues, whereas KLHL30 did not." (PMID 40493396, 2025).
KLHL30 also shares sentences with these, for which no sentence is quoted: liver cancer (1 paper).